FBLIM1 (filamin binding LIM protein 1)
Description:
Serves as an anchoring site for cell-ECM adhesion proteins and filamin-containing actin filaments. Is implicated in cell shape modulation (spreading) and motility. May participate in the regulation of filamin-mediated cross-linking and stabilization of actin filaments. May also regulate the assembly of filamin-containing signaling complexes that control actin assembly. Promotes dissociation of FLNA from ITGB3 and ITGB7. Promotes activation of integrins and regulates integrin-mediated cell-cell adhesion.
Synonyms: FBLP-1; FBLP1; CAL; migfilin
Tractability: No criterion of Open Targets' tractability assessment is met for any kind of drug.
Gene: Protein-coding gene on chromosome 1 (15,756,604 to 15,786,594, forward strand). Ensembl gene ENSG00000162458.
Subcellular location: Cell junction, focal adhesion; Cytoplasm, cytoskeleton, stress fiber
Subcellular location (Human Protein Atlas): Cell Junctions; Focal adhesion sites; Nucleoli fibrillar center
Pathways (Reactome):
Cell-Cell communication: Cell-extracellular matrix interactions
Gene Ontology:
Molecular function: filamin binding; protein binding
Biological process: cell-cell adhesion; regulation of integrin activation
Cellular component: cell junction; cell periphery; cytoplasm; focal adhesion; stress fiber; cytosol
Genetic constraint (gnomAD): Loss-of-function variants: 25 observed, 32.47 expected, observed/expected ratio (o/e) 0.77, 90% interval 0.56 to 1.08. The upper end of that interval is the gene's LOEUF score, 1.08, which puts it in group 4 of 6, group 1 being the genes least tolerant of losing a copy. Missense variants: 407 observed, 457.56 expected, observed/expected ratio (o/e) 0.89, 90% interval 0.82 to 0.97. Synonymous variants: 173 observed, 180.39 expected, observed/expected ratio (o/e) 0.96, 90% interval 0.85 to 1.09.
Homologues: Orthologues: macaque FBLIM1 (95% identical), pig FBLIM1 (85% identical), dog FBLIM1 (83% identical), chimpanzee FBLIM1 (82% identical), rabbit FBLIM1 (81% identical), rat Fblim1 (79% identical), mouse Fblim1 (78% identical), guinea pig FBLIM1 (77% identical), tropical clawed frog fblim1 (44% identical), zebrafish fblim1 (31% identical). Paralogues in human: LPP (33% identical).
Diseases named in the same sentence as FBLIM1 in open-access papers:
FBLIM1 is named in the same sentence as 24 diseases in open-access papers, as found by Europe PMC text mining. Sharing a sentence is not in itself a finding about the gene and the disease. The quoted sentences say what the papers report.
glioma (6 papers, 2018 to 2023). A benign or malignant brain and spinal cord tumor that arises from glial cells (astrocytes, oligodendrocytes, ependymal cells). "Collectively, our study underlined that FBLIM1 was elevated in glioma, and FBLIM1 had prognostic power in glioma, signifying that glioma had vital modulatory functions in gliomas." (PMID 38152333, 2023). "By elucidating the expression, clinical significance, potential functions, and its association with immune infiltration of FBLIM1, this research had the potential to offer new insights and strategies for the diagnosis and treatment of gliomas." (PMID 38152333, 2023). "In order to explore the association between FBLIM1 expression and clinicopathologic features in glioma, we manually divided glioma patients into two groups (high and low-expression groups) based on the mean expression of FBLIM1." (PMID 38152333, 2023). "Significantly, when glioma samples were compared to normal brain samples, FBLIM1 expression was shown to be significantly elevated in the former." (PMID 38152333, 2023). "Overall, FBLIM1 mRNA was shown to be significantly expressed in glioma, and its potential as a predictor of a positive result for glioma is being investigated." (PMID 38152333, 2023). "To explore the possible function of FBLIM1 in glioma, we screened DEGs between FBLIM1-low and -high expression glioma groups, and 420 DEGs were identified." (PMID 38152333, 2023). "To examine FBLIM1 expression in glioma, we performed RT-PCR and found that the FBLIM1 level was distinctly elevated in three glioma cells compared with normal brain cells." (PMID 38152333, 2023). "Then, we explored the connection between the levels of FBLIM1 expression and the clinical pathological characteristics of glioma." (PMID 38152333, 2023). "In this study, we aimed to explore the expression, clinical significance, and potential function of FBLIM1 in glioma patients." (PMID 38152333, 2023). "On the other hand, the prognostic power of the FBLIM1 level was assessed in glioma patients from the CGGA datasets." (PMID 38152333, 2023). "First, we compared the differential FBLIM1 expression in normal tissues and glioma samples using the glioma RNA-seq data provided by TCGA and CGGA." (PMID 38152333, 2023). "Due to the absence of information on the expression levels of other proteins except for FBLIM1, we were unable to investigate the direct mechanism by which FBLIM1 contributes to the progression of glioma." (PMID 38152333, 2023). "In our work, we found a novel glioma-related gene FBLIM1, which is highly expressed in many types of tumors, including glioma." (PMID 38152333, 2023). "In the end, we deciphered the connection between immune infiltration and FBLIM1 expression, as well as its mechanism in the process of developing and promoting glioma." (PMID 38152333, 2023). "Functional experiments unveiled that the knockdown of FBLIM1 mRNA suppressed glioma cell proliferation." (PMID 38152333, 2023). "FBLIM1 was reported to promote migration and invasion in glioma, and participate in brain development and autism spectrum disorders." (PMID 32508873, 2020). "Expression of FBLIM1 correlates with tumor grade and poor prognosis and promotes migration and invasion in glioma." (PMID 30053867, 2018). "In addition, there was a dysregulated level of FBLIM1 in glioma patients with different 1p/19q codeletion and IDH status." (PMID 38152333, 2023). "Importantly, multivariate assays also validated that FBLIM1 level was regarded as a prognostic factor for OS for glioma patients." (PMID 38152333, 2023). "FBLIM1 might be a prognostic index in glioma following the univariate and multivariate Cox analyses." (PMID 38152333, 2023). "In general, we initially discovered that FBLIM1 mRNA might be a possible prognostic marker in glioma." (PMID 38152333, 2023). "Our findings suggested the essentiality of FBLIM1 in the clinical progression of glioma patients." (PMID 38152333, 2023).
glioma (continued). "Notably, multivariate analyses demonstrated that FBLIM1 expression was an independent predictor for the overall survival of glioma patients." (PMID 38152333, 2023). "In addition, we also provided evidence that the knockdown of FBLIM1 distinctly suppressed the biological functions of glioma cells." (PMID 38152333, 2023). "The results of RT-PCR suggested that FBLIM1 expression was markedly elevated in glioma specimens." (PMID 38152333, 2023). "FBLIM1 promotes cell migration and invasion in human glioma by altering the PLC-γ/STAT3 signaling pathway and could be used as a molecular marker for early diagnosis in glioma patients." (PMID 33808029, 2021). "Interestingly, FBLIM1 expression is reduced in breast cancer and has also been shown to sensitize glioma cells to cisplatin-induced apoptosis." (PMID 30285865, 2018). "The current findings point to the possibility that FBLIM1 mRNA might be employed as a potential target to forecast glioma patients’ tumor stage and prognosis, as well as a novel pharmacological target to enhance treatment outcomes and to find new cancer treatments." (PMID 38152333, 2023). "Based on functional enrichment analysis, FBLIM1 may play multiple significant roles in glioma." (PMID 38152333, 2023). "In addition, we investigated the potential role that FBLIM1 plays in glioma prognosis." (PMID 38152333, 2023). "Moreover, the predictive power of FBLIM1 expression was estimated by the ROC analysis, which unveiled that FBLIM1 expression could, respectively, forecast the 1-year (0.772), 3-year (0.788), and 5-year (0.729) survival of glioma patients in an effective way." (PMID 38152333, 2023). "Furthermore, the expression levels of several genes (PLOD3, SLC20A1, ADAM9, FBLIM1, SPOCD1, P4HB, PROS1 and SELENON) were positively correlated with glioma grades." (PMID 32091665, 2020). "It has not been determined, to the best of our knowledge, whether FBLIM1 was expressed or functions in gliomas." (PMID 38152333, 2023). "Importantly, we observed that FBLIM1 expression was notably elevated in glioma specimens versus non-tumor specimens." (PMID 38152333, 2023). "However, the potential function of FBLIM1 mRNA in glioma has not been investigated." (PMID 38152333, 2023).
hepatocellular carcinoma (5 papers, 2020 to 2025). A malignant tumor that arises from hepatocytes. "CircFBLIM1 functions as a miR-346 sponge to regulate FBLIM1 expression, thus promoting hepatocellular cancer progression." (PMID 34420031, 2021). "CircFBLIM1 serves as a ceRNA to regulate FBLIM1 expression via interacting with miR-346 to promote carcinogenesis in hepatocellular cancer." (PMID 32493490, 2020). "FBLIM1 was mentioned to enhance oral cancer malignancy in a previous study and may contribute to the diagnosis of hepatocellular cancer." (PMID 37779184, 2023). "LA14 alleviated the d-GalN-induced upregulation of ROCK2, FBLIM1, and COL12A1, which suggested that LA14 might contribute to the prevention of hepatocellular cancer during acute liver injury." (PMID 34128694, 2021).
chronic recurrent multifocal osteomyelitis (4 papers, 2017 to 2023). "The FBLIM1 role in sterile bone inflammation is confirmed by a mouse model (Pstpip2-deficient) with chronic multifocal osteomyelitis that showed levels of FBLIM1 gene expression downregulated up to 20-fold compared to healthy mice." (PMID 36980060, 2023).
melanoma (2 papers, 2012 to 2020). A malignant, usually aggressive tumor composed of atypical, neoplastic melanocytes. "Curiously, some of them displayed significantly up-regulation upon 5AzaCdR treatment in 4C11+ melanoma cell such as Fblim1, a cytoskeleton regulator that can control integrin activation and cancer progression." (PMID 22984562, 2012). "As a result, we found a significant enrichment in Fblim1 gene expression in 4C11− and 4C11+ melanoma cell lines when compared with melan-a melanocyte lineage." (PMID 22984562, 2012). "Using the real datasets obtained from melanoma patients, we showed that Cyclum can accurately infer the cell-cycle expression components, nominate novel cell-cycle genes (e.g., KCNQ1OT1 and FBLIM1), and elucidate latent associations between cell subpopulations and drug resistance." (PMID 32188848, 2020). "Besides that, the 4C11+ metastatic melanoma cell line showed a progressive enhancement of Fblim1 gene expression as follows: TSA alone (> 3.5), 5AzaCdR alone (> 5), and 5AzaCdR plus TSA (> 6.5 times increase) treatment." (PMID 22984562, 2012). "The 4C11− non-metastatic melanoma cell line showed no significant change in Fblim1 expression when treated with TSA alone." (PMID 22984562, 2012).
Oral cancer (2 papers, 2023). "Oral cancer cells were much less able to proliferate, migrate, and invade when FBLIM1 was knocked down, and this suppression was achieved by modification of the EGFR pathway." (PMID 38152333, 2023). "Based on these findings, FBLIM1 may be an oncogene that contributes to the development of oral cancer." (PMID 38152333, 2023). "According to the findings of a recent study, FBLIM1 is abundantly expressed in oral cancer." (PMID 38152333, 2023). "Furthermore, inhibiting FBLIM1 was revealed to hinder oral cancer cell proliferative, migratory, and invasive properties via modulating the pathway that is controlled by EGFR." (PMID 38152333, 2023).
adenoma (1 paper, 2023). A neoplasm arising from the epithelium. "H ROC analysis for FBLIM1 predicting aberrant methylation in adenoma." (PMID 37779184, 2023). "Five hypermethylated genes including ZNF471, SND1, SPOCK1, FBLIM1, and OTX1 were detected and confirmed in 68 cases of colorectal cancer, 31 cases of adenoma, and 49 cases of normal control group." (PMID 37779184, 2023). "Our results indicated that ZNF471, SND1, SPOCK1, FBLIM1, and OTX1 methylation may be useful in diagnosing colorectal cancer and adenoma." (PMID 37779184, 2023). "Hypermethylated genes of ZNF471, SND1, SPOCK1, FBLIM1, and OTX1 were obtained from methylation chip detection and further confirm analysis in colorectal cancer and adenoma compared with normal tissue, which may be promising diagnostic markers of CRC and colorectal adenoma." (PMID 37779184, 2023). "Hypermethylated genes of ZNF471, SND1, SPOCK1, FBLIM1, and OTX1 were obtained from methylation chip detection and further confirm analysis in colorectal cancer and adenoma compared with normal tissue, which may be promising diagnostic markers of colorectal cancer and colorectal adenoma." (PMID 37779184, 2023).
colorectal adenoma (1 paper, 2023). An adenoma that arises from the colon or rectum. "In our study, hypermethylated FBLIM1 was first found in CRC and colorectal adenoma and the role of FBLIM1 in tumor development and progress is worth further study." (PMID 37779184, 2023). "The methylation degree of ZNF471 was more than 2.9-fold, SND1 was more than 14.5-fold, SPOCK1 was more than 5.8-fold, FBLIM1 was more than 11.1-fold, and OTX1 was more than 6.9-fold in colorectal cancer or colorectal adenoma to that in the normal control." (PMID 37779184, 2023). "Our results showed that all the genes of ZNF471, SND1, SPOCK1, FBLIM1, and OTX1 methylation with the area under receiver operating curve (ROC) more than 0.90 were significantly high in the colorectal adenoma and CRC compared with the normal group." (PMID 37779184, 2023). "Based on the results of the methylation chip of Illumina Infinium 450K detection and bioinformatic analysis, five hypermethylated genes, ZNF471, SND1, SPOCK1, FBLIM1, and OTX1, were selected for further investigation in the colorectal adenoma, CRC, and control normal tissues in our study." (PMID 37779184, 2023).
colorectal cancer (1 paper, 2023). A primary or metastatic malignant neoplasm that affects the colon or rectum. "It is essential that the methylation degree of SND1 was more than 18.1-fold and FBLIM1 was more than 12.4-fold in colorectal cancer to that in the normal control." (PMID 37779184, 2023). "I ROC analysis for FBLIM1 predicting aberrant methylation in colorectal cancer." (PMID 37779184, 2023).
metastatic melanoma (1 paper, 2012). A melanoma that has spread from its primary site to another anatomic site. "Furthermore, we investigated the differential expression of genes HSPB1, SERPINE1 and FBLIM1 in a panel of five patient-derived metastatic melanoma cell lines in comparison to FM305 primary melanocytes." (PMID 22984562, 2012).
non-alcoholic fatty liver disease (1 paper, 2023). "FBLIM1 was hypomethylated and could reduce cell proliferation in non-alcoholic fatty liver disease." (PMID 37779184, 2023).
Osteopenia (1 paper, 2017). Osteopenia is a term to define bone density that is not normal but also not as low as osteoporosis. "Mice null for FBLIM1 have severe osteopenia and increased osteoclast differentiation marked by increased RANKL expression in bone marrow stromal cells." (PMID 28301468, 2017).
renal fibrosis (1 paper, 2016). A final common manifestation of a wide variety of chronic kidney diseases characterized by glomerulosclerosis and tubulointerstitial fibrosis. "The list of genes includes Fblim1, Epha2, Wisp1, Parvg, Madcam1, Mybpc2, Cdh3, Gpr56, Troap, Pstpip1, Pcdh8, Nlgn2 and Mfap4, genes that based on Pubmed and Kidney and Urinary Pathway Knowledge Base12 searches have not been previously associated with renal fibrosis." (PMID 27189340, 2016).
SAPHO syndrome (1 paper, 2020). SAPHO syndrome (acronym for Synovitis, Acne, Pustulosis, Hyperostosis and Osteitis) is an auto-inflammatory disease, mainly characterized by the association of neutrophilic cutaneous involvement and chronic osteomyelitis. "Findings of this new potential candidate gene FBLIM1 in CRMO prompted us to analyze our cohort of CRMO and SAPHO syndrome patients for rare coding variants in FBLIM1." (PMID 32397996, 2020). "Still, when considering SAPHO syndrome and CRMO as part of the same disease spectrum, our study does not support FBLIM1 as a disease gene." (PMID 32397996, 2020).
tumor (6 papers, 2018 to 2025). "Also, a correlation was found between the expression of FBLIM1 and the size of the main tumor and its vascular invasion." (PMID 38152333, 2023). "However, the expression trend of FBLIM1 was different in different tumors, suggesting that it may serve as a tumor promotor or a tumor suppressor according to the types of tumors." (PMID 38152333, 2023). "Among the top of the list sorted by the smallest adjusted P values were five genes: ADHFE1, EYA4, FBLIM1, HOXA3, and HOXA5, all hypermethylated in all tumor groups." (PMID 40753397, 2025). "Of 22 differentially methylated promoters common between all LS tumor groups, seven inversely correlated with expression: ADHFE1, DAPP1, FBLIM1, GRIA4, HOXA3, KLF17, and ZNF528." (PMID 40753397, 2025). "Initially, FBLIM1 mRNA expression in the tumor samples of GTEx coupled with TCGA and the corresponding normal samples of TCGA were compared for the pan-cancer analysis by the Wilcoxon rank sum test." (PMID 38152333, 2023).
cancer (5 papers, 2012 to 2023). A tumor composed of atypical neoplastic, often pleomorphic cells that invade other tissues. "Recently, a few studies have implicated FBLIM1 in cancer metastasis." (PMID 30053867, 2018). "Unfortunately, there is limited information on the role of FBLIM1 in cancers." (PMID 38152333, 2023). "The positive correlation between FBLIM1 (filamin binding LIM protein 1) and SRC (v-srcsarcoma viral oncogene homolog [avian]) overexpression resulted in anoikis resistance contributing to tumorigenicity of established carcinoma cells." (PMID 22984562, 2012).
inflammation (1 paper, 2017). Aberrant reaction of the microcirculation characterized by movement of fluid and leukocytes from the blood into extravascular tissues. "Our data implicate FBLIM1 in the pathogenesis of sterile bone inflammation and our findings suggest CRMO is a disorder of chronic inflammation and imbalanced bone remodeling." (PMID 28301468, 2017).
FBLIM1 also shares sentences with these, for which no sentence is quoted: Arthritis (1 paper); autism spectrum disorder (1); breast carcinoma (1); gastric cancer (1); Hypercalcemia (1); laryngeal squamous cell carcinoma (1); lung carcinoma (1); prostate carcinoma (1).